MICALL2 (MICAL like 2)
Description:
Effector of small Rab GTPases which is involved in junctional complexes assembly through the regulation of cell adhesion molecules transport to the plasma membrane and actin cytoskeleton reorganization. Regulates the endocytic recycling of occludins, claudins and E-cadherin to the plasma membrane and may thereby regulate the establishment of tight junctions and adherens junctions. In parallel, may regulate actin cytoskeleton reorganization directly through interaction with F-actin or indirectly through actinins and filamins. Most probably involved in the processes of epithelial cell differentiation, cell spreading and neurite outgrowth (By similarity). Undergoes liquid-liquid phase separation to form tubular recycling endosomes. Plays 2 sequential roles in the biogenesis of tubular recycling endosomes: first organizes phase separation and then the closed form formed by interaction with RAB8A promotes endosomal tubulation (By similarity).
Synonyms: MICAL-L2; JRAB; MGC46023; FLJ23471
Tractability: Antibody: UniProt places it where antibodies can reach, with medium confidence; its Gene Ontology location is reachable by antibodies, with medium confidence. PROTAC: its protein half-life has been measured.
Gene: Protein-coding gene on chromosome 7 (1,428,465 to 1,459,496, reverse strand). Ensembl gene ENSG00000164877.
Subcellular location: Cell membrane; Cell junction, tight junction; Recycling endosome; Cell projection; Cytoplasm, cytoskeleton
Gene Ontology:
Molecular function: filamin binding; protein binding; actin filament binding; small GTPase binding; actinin binding
Biological process: positive regulation of establishment of protein localization to mitochondrion; actin cytoskeleton organization; actin filament polymerization; bicellular tight junction assembly; endocytic recycling; neuron projection development; substrate adhesion-dependent cell spreading; endosome membrane tubulation; Rab protein signal transduction
Cellular component: actin filament bundle; bicellular tight junction; cell-cell junction; neuron projection; plasma membrane; recycling endosome; stress fiber; cytoskeleton
Genetic constraint (gnomAD): Loss-of-function variants: 110 observed, 76.95 expected, observed/expected ratio (o/e) 1.43, 90% interval 1.22 to 1.67. The synonymous counts are far from expectation, so gnomAD's model fits this gene poorly and the ratio says little. Missense variants: 1,515 observed, 1,095.4 expected, observed/expected ratio (o/e) 1.38, 90% interval 1.33 to 1.44. Synonymous variants: 672 observed, 466.03 expected, observed/expected ratio (o/e) 1.44, 90% interval 1.35 to 1.54.
Homologues: Orthologues: chimpanzee MICALL2 (98% identical), macaque MICALL2 (82% identical), pig MICALL2 (65% identical), dog MICALL2 (63% identical), guinea pig MICALL2 (62% identical), mouse Micall2 (60% identical), rat Micall2 (58% identical), tropical clawed frog micall2 (40% identical), zebrafish micall2b (32% identical), zebrafish micall2a (31% identical), Drosophila melanogaster Ehbp1 (12% identical). Paralogues in human: MICALL1 (30% identical), ASPM (16% identical), EHBP1L1 (16% identical), EHBP1 (15% identical), GAS2L1 (10% identical), SMTNL1 (8% identical), GAS2 (6% identical).